FTH1P24 (ferritin heavy chain 1 pseudogene 24)
Synonyms: TCLlnc1; formerly FTHL24
Gene: Processed pseudogene on chromosome 4 (139,546,266 to 139,546,727, forward strand). Ensembl gene ENSG00000249302.
Diseases named in the same sentence as FTH1P24 in open-access papers:
FTH1P24 is named in the same sentence as 5 diseases in open-access papers, as found by Europe PMC text mining. Sharing a sentence is not in itself a finding about the gene and the disease.
FTH1P24 shares sentences with these, for which no sentence is quoted: lymphoma (2 papers); tumor (2); acute leukemia (1); peripheral T cell lymphoma (1); T cell lymphoma (1).